KIAA0087 (KIAA0087 lncRNA)
Gene: Long non-coding RNA gene on chromosome 7 (26,533,121 to 26,538,859, reverse strand). Ensembl gene ENSG00000122548.
Diseases named in the same sentence as KIAA0087 in open-access papers:
KIAA0087 is named in the same sentence as 4 diseases in open-access papers, as found by Europe PMC text mining. Sharing a sentence is not in itself a finding about the gene and the disease. The quoted sentences say what the papers report.
tumor (1 paper, 2023). "Obvious decreases in tumor weight and volume in the KIAA0087-overexpression or miR-411-3p-inhibition group were demonstrated." (PMID 37009803, 2023). "Overexpression of KIAA0087 or inhibition of miR-411-3p increased the E-cadherin level but suppressed the N-cadherin expression level in tumor tissues, suggesting that the EMT process was repressed." (PMID 37009803, 2023). "Finally, in vivo tumor growth and lung metastasis were inhibited in KIAA0087-overexpressing or miR-411-3p-inhibited OS cells." (PMID 37009803, 2023). "In addition, a lower Ki-67 expression level in tumor tissues was confirmed in the KIAA0087-overexpression or miR-411-3p-inhibition group." (PMID 37009803, 2023). "In addition, KIAA0087 overexpression led to a decreased miR-411-3p expression level and an increased SOCS1 expression level in tumor tissues." (PMID 37009803, 2023).
KIAA0087 also shares sentences with these, for which no sentence is quoted: cancer (1 paper); cervical cancer (1); osteosarcoma (1).